CCT6A (chaperonin containing TCP1 subunit 6A)
Diseases named in the same sentence as CCT6A in open-access papers (continued):
Sharing a sentence is not in itself a finding about the gene and the disease.
cancer (continued). "Hierarchical clustering of subunit expression across solid cancers highlighted CCT8 as highly consistently upregulated across all cancers (mean change = 0.76, t test), and as overall second most highly upregulated subunit besides CCT6A (mean change = 0.786, t test)." (PMID 29293508, 2018). "However, the role of CCT6A in most cancers, including OS, remains unknown." (PMID 36584147, 2022). "Some of the genes were reported as cancer-related genes, such as CCT2, CCT3, CCT4, CCT6A, CCT7, CCT8." (PMID 33897772, 2021). "Based on the Oncomine database, we found that mRNA expressions of TCP1, CCT2, CCT6A, CCT7, STIP1 and HSP90AB1 were significantly upregulated in cancerous samples compared with normal samples in various types of cancer, including BC." (PMID 32194784, 2020). "In the end, CCT6A, UTP18, YRDC, RRP12, RFT1, NLE1, and DDOST were essential genes across pan-cancer including COAD cells." (PMID 31867042, 2019). "Moreover, we found that TPD52, TF, and CCT6A were more frequently heterozygous amplified while STC2, CISD1, and P4HA2 were more likely to occur in heterozygous deletion in cancers." (PMID 36998462, 2023). "Dependency score analysis by DepMap showed that ACTG1 and RHOQ were less essential across pan-cancer cells including COAD cell lines, and CCT6A, UTP18, YRDC, RRP12, RFT1, NLE1, as well as DDOST were essential across pan-cancer cells including most of COAD cell lines." (PMID 31867042, 2019). "CCT6A was discovered to be an inhibitor and direct binding protein of SMAD2, and it was shown that CCT6A may block the function of SMAD2 in NSCLC cells and enhance cancer cell metastasis." (PMID 36588537, 2022). "In addition, CCT6A, UTP18, YRDC, RRP12, RFT1, NLE1, as well as DDOST were essential genes across pan-cancer including COAD cells, and ACTG1 and RHOQ were less essential genes in cancer cells." (PMID 31867042, 2019).
infection (2 papers, 2019 to 2025). The state of being infected such as from the introduction of a foreign agent such as serum, vaccine, antigenic substance or organism. "The successful silencing of CCT6A was confirmed by western blotting analysis following the infection of PDAC cells with shRNA-expressing lentivirus." (PMID 40374617, 2025).
CCT6A also shares sentences with these, for which no sentence is quoted: liver cancer (4 papers); gastric cancer (2); Lung Squamous Cell Carcinoma (2); renal cell carcinoma (2); adenocarcinoma (1); blastoma (1); breast tumors (1); cervical squamous cell carcinoma (1); colon adenocarcinoma (1); diabetes (1); endocervical adenocarcinoma (1); Ewing sarcoma (1); head and neck squamous cell carcinoma (1); hyperlipidemia (1); Hypertension (1); Intellectual disability (1); leukodystrophy (1); metastasis (1); neurodegenerative disease (1); oral cancer (1); ovarian carcinoma (1); pancreatic ductal adenocarcinoma (1); prostate carcinoma (1); rectum adenocarcinoma (1); rheumatoid arthritis (1); stomach adenocarcinoma (1); systemic lupus erythematosus (1); virus infection (1).